SCN1A (sodium voltage-gated channel alpha subunit 1)
Diseases named in the same sentence as SCN1A in open-access papers (continued):
Sharing a sentence is not in itself a finding about the gene and the disease.
epilepsy (continued). "Contrary to SCN1A variant-associated epilepsy that revealed seizure was aggravated by sodium channel blockers, ADGRV1 variants were associated with mild epilepsy with favorable responses to antiepileptic drugs." (PMID 35813073, 2022). "In the current study, we reported insignificant differences between epilepsy cases and the control group regarding the SCN1A-A3184G genotypes and alleles." (PMID 36056404, 2022). "We found a strong increase of number of spikes measured in 24 h in Scn1a ± mice after the thermal stress but not in the Scn1a ± eEF2K−/− mice, suggesting that eEF2K deficiency reduced the susceptibility to epilepsy of the Scn1a ± mice." (PMID 34980259, 2022). "We retrospectively collected the clinical and genetic information of 22 epilepsy patients (10 males, 12 females; mean: 9.2 ± 3.9 years; 3.9–20.3 years) carrying 22 variants of SCN1A." (PMID 35663268, 2022). "In this cohort, 24.75% of patients had SCN1A variants, which confirmed the causative role of SCN1A in FS-related epilepsy." (PMID 35813073, 2022). "Mutations to SCN1A lead to epilepsy disorders ranging from simple febrile seizures to the spectrum of generalized epilepsy with febrile seizures plus (GEFS+) disorders." (PMID 35523580, 2022). "SCN1A gene polymorphisms were found to be associated with the therapeutic effects of VPA in the treatment of epilepsy." (PMID 36506519, 2022). "In contrast, most patients with FS and FS-related epilepsy caused by SCN1A variants, such as Dravet syndrome and partial epilepsy with FS plus, were at risk of seizure aggravation induced by sodium channel blocker AEDs." (PMID 35813073, 2022). "Other epilepsy-causative genes, SCN1A and SCN2A, which encode the voltage-gated sodium channels type 1 and 2, respectively, have shown phenotypic differences based on variant types." (PMID 33262389, 2021). "A genetic knock-in model for SCN1A epilepsy in mice carrying the GEFS+ causing R1648H mutation, results in animals that exhibit heat-induced seizures as well as sleep, cognitive and social behavior deficits." (PMID 33658306, 2021). "SCN1A, SCN2A, SCN3A, and SCN8A genes which individually encode voltage-gated sodium channels, that is NaV1.1, NaV1.2, NaV1.3, and NaV1.6, are related to early onset epilepsies." (PMID 34276290, 2021). "An SCN1A variant c.4868A>C/p.E1623A was identified from two cases of epilepsy, including a case with de novo variant and a familial case with three individuals affected." (PMID 35082603, 2021). "It is an interesting observation that mutations in the same gene SCN1A cause 2 different diseases, with most mutations causing either migraine or epilepsy." (PMID 34546973, 2021). "Although most SCN1A-associated epilepsies are considered a loss-of-function disease, our results put L1624Q into a growing set of mixed gain and loss-of-function variants in SCN1A responsible for an increasing set of epilepsy phenotypes." (PMID 34925043, 2021). "Another form of epilepsy connected with SCN1A mutations, apart from DS, is epilepsy with febrile seizures plus and epilepsy of infancy with migrating focal seizures." (PMID 33924914, 2021). "Although DS and GEFS+ can be used as prototypes to study SCN1A variants, these mutations are also involved in other sub-types of epilepsy." (PMID 33841294, 2021). "The mutation of the SCN1A gene encoding the alpha subunit of the Nav1.1 channel leads to Epilepsy with various clinical phenotypes 114-116." (PMID 33390815, 2021). "One had SCN1A G682V and other had 2 SCN1A variants in cis: L1296M and E1308D variants which were previously known to be associated with epilepsy." (PMID 34722422, 2021). "With increased genetic testing, SCN1A variants have been described in patients with focal epilepsies —both in patients that were candidates for epilepsy surgery, and those with self-limiting focal epilepsies of childhood." (PMID 34925043, 2021).
epilepsy (continued). "Mutations in SCN1A, the gene encoding the type I voltage-gated sodium channel Nav1.1, are associated with a family of epilepsies in which febrile seizures are the minimum epileptic phenotype." (PMID 34733140, 2021). "This highlights the importance of individualized therapy for patients with SCN1A related epilepsies, and the need for a better understanding of the range of epilepsy-causing variants." (PMID 34925043, 2021). "The human SCN1A gene (the ortholog of the zebrafish scn1lab gene) is associated with Dravet’s syndrome (where patients have epilepsy and developmental disorders including autism), and DISC1 is associated with schizophrenia." (PMID 34613782, 2021). "Among variants transmitted from heterozygous carrier parents within cardiac or seizure disorder genes, two variants associated with autosomal dominant conditions were classified as contributory to death in two cases (SCN1A and DEPDC5)." (PMID 34930847, 2021). "Based on these findings, it is plausible that pathogenic variation in regulatory regions modulates SCN1A transcription, contributing to epilepsy." (PMID 33910599, 2021). "Mice with heterozygous deletion of Scn1a (Scn1a+/−) model Dravet syndrome, a severe epilepsy most often caused by SCN1A haploinsufficiency." (PMID 34086081, 2021). "The phenotypical spectrum of SCN1A mutations spans from mild to severe epilepsies, all characterized by fever-sensitive seizures." (PMID 34842787, 2021). "Regardless, our findings show the relevance of this novel Scn1a regulatory deletion mouse line to SCN1A-associated epilepsy." (PMID 33910599, 2021). "Some SCN1A mutations that lead to either Dravet syndrome (DS) or GEFS+ epilepsy have been correlated with premature death in mouse models." (PMID 33658306, 2021). "With more than 175 mutations reported to date, PCDH19 is now clinically considered as the second major disease gene implicated in epilepsy, after SCN1A." (PMID 34201522, 2021). "In a meta-analysis of genome-wide association studies (GWAS) across unselected epilepsies, SCN1A is one of only few genes with a significant association with epilepsy." (PMID 34925043, 2021). "The K1270T SCN1A knock-in mice represent an important tool for identifying similarities and differences in mechanism of action with R1648H and other epilepsy mutations, and for development of mutation-specific therapies." (PMID 33658306, 2021). "The patients with SCN1A variants presented with early-onset seizures, drug-resistant epilepsy, developmental slowing and cognitive impairment, consistent with previous findings." (PMID 34163418, 2021). "Pathogenic variants in the SCN1A gene are associated with a spectrum of epilepsy phenotypes ranging in severity from familial febrile seizures (FSs) on the mild end to DS on the other." (PMID 34938262, 2021). "Despite the strong association between variants of the SCN1A gene and Dravet syndrome, there is considerable heterogeneity in the phenotypes of SCN1A associated epilepsies." (PMID 34925043, 2021). "In the sodium channel gene SCN1A, there are >1250 dominantly inherited mutations identified in patients with epilepsy." (PMID 34475263, 2021). "Although loss-of-function variants are associated with a more severe phenotype in SCN1A, the molecular mechanism of single nucleotide variants is often not clear, and genotype-phenotype correlations in SCN1A-related epilepsy remain uncertain." (PMID 34938262, 2021). "Over 1300 genetic mutations in SCN1A, a gene that encodes the voltage gated sodium channel Nav1.1, are associated with epilepsies of widely different severity." (PMID 33658306, 2021). "Here, we focussed on correcting metabolic defects in a catastrophic paediatric epilepsy, Dravet syndrome which is caused by mutations in sodium channel NaV1.1 gene, SCN1A." (PMID 33842883, 2021).
epilepsy (continued). "Mutations in SCN1A, which encodes the NaV1.1 sodium channel alpha subunit, result in a range of epilepsy phenotypes from generalized febrile seizures to Dravet syndrome (DS), a severe childhood-onset disorder." (PMID 33910599, 2021). "Multiple mutations in SCN1a are associated with childhood epilepsies such as Dravet and GEFs and there are already several mouse models available to model these." (PMID 33658306, 2021). "A nonsense variant within this exon or an out-of-frame aberrant transcript will trigger NMD or produce a truncated form of SCN1A protein, therefore reduce the amount of full-length SCN1A protein, and cause epilepsy due to haploinsufficiency." (PMID 34107977, 2021). "While most SCN1A-related epilepsies are typically considered a loss-of-function disease, our results put L1624Q into a growing set of mixed gain and loss-of-function variants in SCN1A responsible for early childhood epilepsy." (PMID 34925043, 2021). "SCN1A gene, which encodes NaV1.1 subunit expressed in inhibitory GABA neurons, has also been implicated in the mutations of SCN1A in epilepsy patients." (PMID 33746751, 2021). "Almost 90% of DS patients carry a SCN1A mutation, which is also the most prominent epilepsy gene in general." (PMID 34948153, 2021). "In this study, we identified a novel distinct missense SCN1A variant (c.4868A>C/E1613A) in two cases with epilepsy and febrile seizures." (PMID 35082603, 2021). "Genetic defects in voltage-gated sodium channel (Nav1.1) α subunit encoded by SCN1A are a major cause of epilepsy." (PMID 35082603, 2021). "Mouse models with heterozygous coding mutations in Scn1a recapitulate features of DS, including seizures and sudden unexpected death in epilepsy (SUDEP)." (PMID 33910599, 2021). "This is a solid study in which the authors develop a murine model of a sodium channel mutation (SCN1A K>T) implicated in epilepsies." (PMID 33658306, 2021). "SCN1A encodes the alpha subunit of the neuronal voltage gated sodium channel NaV1.1 and variants of this gene are known to cause a variety of epilepsy phenotypes in humans." (PMID 34925043, 2021). "Clinical and genetic data were compared to those of other 10 previously published patients with epilepsy and variants in compound heterozygosity or homozygosity in the SCN1A gene." (PMID 34917021, 2021). "A role for genetic background in contributing to disease phenotype is not inconsistent with clinical data indicating that the severity of seizure disorders can vary even between individuals with the same SCN1A mutation." (PMID 34475263, 2021). "SCN1A mutations are the most prevalent amongst all VGSCs mutations in epilepsy and over 1,250 pathogenic variants are responsible for various epilepsies." (PMID 33841294, 2021). "Understanding the functional effects of unique mutants, particularly when associated with unusual phenotypes, is an essential next step for understanding genotype-phenotype relationships in SCN1A-associated epilepsies." (PMID 34925043, 2021). "The case presented here represents an extension of the SCN1A-associated epilepsy phenotypes with the clinical features of an epilepsy syndrome classically associated with different genetic causes." (PMID 34925043, 2021). "In a study, researchers applied CRISPR/Cas9 and TALEN-mediated gene-editing techniques to iPSCs-based disease models to explore the pathogenesis of Epilepsy caused by SCN1A functional deletion mutations." (PMID 33390815, 2021). "Dravet Syndrome (DS) is a severe childhood epilepsy caused by heterozygous loss-of-function mutations in the SCN1A gene encoding brain type-I voltage-gated sodium channel Nav1.1." (PMID 34308420, 2021). "Genetic loci associated with epilepsy (2q24.3) included two different sodium channel genes (rs6432860 in SCN1A and rs3769955 in SCN2A)." (PMID 33841294, 2021).
epilepsy (continued). "In the same year, Zhang and colleagues found 46 cases of genetic mutations in 253 children with unexplained epilepsy and intellectual/developmental disabilities, of which only one was an SCN1A mutation causing malignant migrating partial seizures of infancy." (PMID 35002916, 2021). "For SCN1A, familial cases have initially helped establish an association with epilepsy in the context of generalized epilepsy with febrile seizures plus (GEFS+)." (PMID 34925043, 2021). "Loss of function mutations of SCN1A, the gene coding for the voltage-gated sodium channel NaV1.1, cause different types of epilepsy, whereas gain of function mutations cause sporadic and familial hemiplegic migraine type 3 (FHM-3)." (PMID 34314446, 2021). "Among genes reported to be associated with epilepsy, the SCN1A gene, which encodes the type 1 sodium channel alpha-subunit, stands out as for being most highly associated with epilepsy." (PMID 34868252, 2021). "But with the increased availability of genetic testing for patients with epilepsy, variants in SCN1A have now also been described in a range of other epilepsy phenotypes." (PMID 34925043, 2021). "Possible predictive factors for SE with AE include early age at epilepsy onset (<6 m), epilepsy severity and recurrent SE, age under five years, and truncating SCN1A mutation." (PMID 33238377, 2020). "Given the genetic complexity of epilepsy, different genes cause specific epilepsy subtypes that are clinically indistinguishable and on the other hand, monogenic SNPs like in SCN1A cause varied phenotypes, from febrile seizure to epileptic encephalopathies." (PMID 33096746, 2020). "For instance, SCN1A, a voltage-dependent sodium channel gene is known to be associated with epilepsy." (PMID 32984858, 2020). "The most severe phenotype associated with SCN1A mutations is Dravet syndrome (DS; MIM#607208), which accounts for >80% epilepsy patients carrying SCN1A mutations." (PMID 32581296, 2020). "SCN1A mutations are found in up to 80% of patients with Dravet syndrome, a type of epilepsy observed in infancy, and sudden unexpected death results in 38% of all deaths in patients with a childhood onset." (PMID 32508047, 2020). "We investigate the presence of rare and more common variants in epilepsy‐related genes as potential modifiers of SCN1A‐related disease severity." (PMID 32032478, 2020). "In almost 50% of epilepsy patients, SCN1A mutations arise de novo, whereas only around 9% of the patients inherit the mutation from an unaffected parent." (PMID 32581296, 2020). "SCN1A (OMIM #182389) is one of the most important epilepsy‐related genes, with pathogenic variants leading to a wide range of phenotypes with varying disease severity." (PMID 32032478, 2020). "Deleterious SCN1A mutations cause uncommon monogenic forms of epilepsy, and common variants increase the risk for more typical sporadic forms of epilepsy." (PMID 32714261, 2020). "Behavioral seizures in Scn1a KO-induced epilepsy models show that SCN1A deficiency increases susceptibility to seizures; however, treatment with Lira can reduce susceptibility and severity." (PMID 32184723, 2020). "Except for the epilepsy-associated SCN1A/para, which was exclusively expressed in both the larval central nervous system (CNS) and adult brain tissues, the other tested neurodevelopmental genes were also expressed in non-neuronal tissues." (PMID 32579612, 2020). "Actually, SCN9A variant is often mentioned as a genetic modifier in SCN1A mutation-associated epilepsy." (PMID 32062735, 2020). "SCN1A is one of the most important epilepsy‐related genes, with pathogenic variants leading to a range of phenotypes with varying disease severity." (PMID 32032478, 2020). "The Chr2q24 linked region encompassed ~65 genes including the known epilepsy gene cluster (SCN1A, SCN2A and SCN3A)." (PMID 33216760, 2020).
epilepsy (continued). "Variants in epilepsy‐associated VGSC genes expressed in the central nervous system have also been associated with SUDEP: SCN1A, SCN2A, and SCN8A." (PMID 32449611, 2020). "Initial studies in induced pluripotent stem cell (iPSC)‐derived neurons and mouse models of SCN1A, traditionally associated with epilepsy, suggested cardiac and/or respiratory mechanisms of death." (PMID 32449611, 2020). "These epilepsy-causing SCN1A mutations are found in transmembrane segments S1 and S2 of domain III in the sodium channels." (PMID 32899411, 2020). "Five different genes that encode alpha subunits of sodium ion channels have been reported to have mutations that lead to epilepsy; these include SCN1A, SCN2A, SCN3A, SCN8A, and SCN9A, and epilepsy-inducing mutations have also been reported in SCN1B." (PMID 33102526, 2020). "Excitatory/inhibitory imbalance has been described in a variety of epilepsy models, with Scn1a‐linked DS mice serving as the first example of impaired inhibitory interneuron excitability driving epileptogenesis." (PMID 32979291, 2020). "Mutations in the human ortholog, SCN1A, are associated with a wide spectrum of epilepsies with over 600 mutations registered in this sole locus." (PMID 33519685, 2020). "We also examined the effects of biophysical changes associated with mutations in the SCN1A gene that cause epilepsy." (PMID 30705357, 2019). "The consequences of biophysical changes induced by epilepsy-related SCN1A mutations were also examined." (PMID 30705357, 2019). "Variants in STX1B are protean and contribute to many different epilepsy phenotypes, similar to SCN1A, the most important gene associated with fever-associated epilepsies." (PMID 30737342, 2019). "Many other ASD-associated genes like CDKL5, SCN1A are also associated with epilepsy, ID, or other neurological syndromes." (PMID 31031587, 2019). "The SCN1A gene encodes a subunit of sodium channel, previously associated with epilepsy and indicated as the candidate gene for ASDs while the LAMC3 gene is expressed in the cortex and limbic system." (PMID 30627967, 2019). "Among epilepsy mutants, zebrafish larvae with loss of function of the scn1Lab gene, one of the two zebrafish orthologs of SCN1A, was instrumental to identify drugs alleviating seizures in refractory epilepsy." (PMID 31590334, 2019). "SCN1A is a well-known epilepsy gene with hundreds of mutations being causative for various forms of epilepsy." (PMID 31730442, 2019). "Currently, SCN1A, which encodes the neuronal voltage-gated sodium channel Nav1.1, is considered one of the most relevant epilepsy-related genes in the clinical setting." (PMID 31001185, 2019). "Dravet syndrome (DS), a severe genetic form of epilepsy, has been associated with mutations in the sodium channel protein type 1 subunit alpha (SCN1A)." (PMID 31096646, 2019). "It has also been shown that epilepsy-related mutations in SCN1A (encoding for Nav1.1) are associated with significantly shortened recurrence-free survival in CRCa patients treated with 5-fluoruracil adjuvant chemotherapy." (PMID 31661908, 2019). "The predominant expression of SCN1A in inhibitory interneurons is in agreement with the finding that most epilepsy mutations reduce Nav1.1 functionality." (PMID 31730442, 2019). "Nevertheless, the clinical outcome of SCN1A missense mutations is difficult to predict, as these de novo mutations can also lead to milder forms of epilepsy." (PMID 30735520, 2019). "In summary, our findings suggest that there are potentially additional causative genetic variants to be identified in and around epilepsy-related genes such as SCN1A, including in predicted poison exons." (PMID 31814998, 2019).